SNAPC4 (small nuclear RNA activating complex polypeptide 4)
Description:
Part of the SNAPc complex required for the transcription of both RNA polymerase II and III small-nuclear RNA genes. Binds to the proximal sequence element (PSE), a non-TATA-box basal promoter element common to these 2 types of genes. Recruits TBP and BRF2 to the U6 snRNA TATA box.
Synonyms: SNAP190; PTFalpha; FLJ13451; NEDRSO
Tractability: Small molecule: a structure with a bound ligand is known. PROTAC: ubiquitination databases record sites on it.
Gene: Protein-coding gene on chromosome 9 (136,375,567 to 136,400,176, reverse strand). Ensembl gene ENSG00000165684.
Subcellular location: Nucleus
Subcellular location (Human Protein Atlas): Nuclear membrane; Nucleoplasm
Pathways (Reactome):
Gene expression (Transcription): RNA Polymerase III Abortive And Retractive Initiation; RNA Polymerase III Transcription Initiation From Type 3 Promoter; RNA polymerase II transcribes snRNA genes
Gene Ontology:
Molecular function: DNA binding; protein binding; RNA polymerase II general transcription initiation factor activity; RNA polymerase III general transcription initiation factor activity; RNA polymerase II cis-regulatory region sequence-specific DNA binding; RNA polymerase III type 3 promoter sequence-specific DNA binding
Biological process: snRNA transcription by RNA polymerase II; snRNA transcription by RNA polymerase III
Cellular component: snRNA-activating protein complex; nucleoplasm; nucleus
Genetic constraint (gnomAD): Loss-of-function variants: 116 observed, 135.98 expected, observed/expected ratio (o/e) 0.85, 90% interval 0.73 to 1. The synonymous counts are far from expectation, so gnomAD's model fits this gene poorly and the ratio says little. Missense variants: 2,137 observed, 1,840.5 expected, observed/expected ratio (o/e) 1.16, 90% interval 1.12 to 1.2. Synonymous variants: 984 observed, 791.46 expected, observed/expected ratio (o/e) 1.24, 90% interval 1.18 to 1.31.
Homologues: Orthologues: chimpanzee SNAPC4 (96% identical), macaque SNAPC4 (89% identical), dog SNAPC4 (65% identical), pig SNAPC4 (63% identical), guinea pig SNAPC4 (60% identical), rat Snapc4 (58% identical), mouse Snapc4 (58% identical), tropical clawed frog snapc4 (34% identical), zebrafish snapc4 (26% identical), Caenorhabditis elegans snpc-4 (12% identical). Paralogues in human: MYBL2 (9% identical), MYB (9% identical), MYBL1 (9% identical), DMTF1 (9% identical), CDC5L (7% identical), TTF1 (6% identical).
Diseases named in the same sentence as SNAPC4 in open-access papers:
SNAPC4 is named in the same sentence as 5 diseases in open-access papers, as found by Europe PMC text mining. Sharing a sentence is not in itself a finding about the gene and the disease. The quoted sentences say what the papers report.
Crohn disease (2 papers, 2020 to 2022). A gastrointestinal disorder characterized by chronic inflammation involving all layers of the intestinal wall, noncaseating granulomas affecting the intestinal wall and regional lymph nodes, and transmural fibrosis. "Our analysis resulted in five candidate genes corresponding to two of the major IBD subtypes: UBE2L3 and SLC22A4 for Crohn’s Disease and TCF19, C6orf47 and SNAPC4 for Ulcerative Colitis." (PMID 34968289, 2020).
ankylosing spondylitis (1 paper, 2025). An autoimmune chronic inflammatory disorder characterized by inflammation in the vertebral joints of the spine and sacroiliac joints. "SNAPC4 is also associated with ankylosing spondylitis, an inflammatory disease that affects the spine, and like IBM, has the MHC implicated in its pathogenesis." (PMID 39815348, 2025).
cancer (1 paper, 2021). A tumor composed of atypical neoplastic, often pleomorphic cells that invade other tissues. "SNAPC4 gene encodes the largest subunit of the small nuclear RNA-activating protein (SNAP) complex, and its role in cancer is unknown." (PMID 34642262, 2021).
SNAPC4 also shares sentences with these, for which no sentence is quoted: thyroid cancer (2 papers); ulcerative colitis (2).